COLEC10 (collectin subfamily member 10)
Description:
Lectin that binds to various sugars: galactose > mannose = fucose > N-acetylglucosamine > N-acetylgalactosamine. Acts as a chemoattractant, probably involved in the regulation of cell migration.
Synonyms: CL-L1; CL-34; CLL1; CL-10; 3MC3
Tractability: Antibody: UniProt places it where antibodies can reach, with high confidence; its Gene Ontology location is reachable by antibodies, with high confidence; UniProt predicts a signal peptide or a membrane-spanning region.
Gene: Protein-coding gene on chromosome 8 (118,995,452 to 119,108,455, forward strand). Ensembl gene ENSG00000184374.
Subcellular location: Secreted; Golgi apparatus; Cytoplasm
Pathways (Reactome):
Immune System: Initial triggering of complement; Lectin pathway of complement activation
Gene Ontology:
Molecular function: chemoattractant activity; protein binding; D-mannose binding
Biological process: complement activation, lectin pathway; cranial skeletal system development; positive regulation of opsonization; proteolysis; cell surface pattern recognition receptor signaling pathway; positive chemotaxis
Cellular component: cytoplasm; extracellular region; external side of plasma membrane; Golgi apparatus; serine-type endopeptidase complex
Genetic constraint (gnomAD): Loss-of-function variants: 10 observed, 15.68 expected, observed/expected ratio (o/e) 0.64, 90% interval 0.39 to 1.08. The upper end of that interval is the gene's LOEUF score, 1.08, which puts it in group 4 of 6, group 1 being the genes least tolerant of losing a copy. Missense variants: 240 observed, 250.51 expected, observed/expected ratio (o/e) 0.96, 90% interval 0.86 to 1.07. Synonymous variants: 91 observed, 90.27 expected, observed/expected ratio (o/e) 1.01, 90% interval 0.85 to 1.2.
Homologues: Orthologues: chimpanzee COLEC10 (99% identical), macaque COLEC10 (99% identical), dog COLEC10 (94% identical), pig COLEC10 (94% identical), rabbit COLEC10 (93% identical), guinea pig COLEC10 (89% identical), mouse Colec10 (89% identical), rat Colec10 (88% identical), tropical clawed frog colec10 (62% identical), zebrafish COLEC10 (41% identical). Paralogues in human: COLEC11 (45% identical), SFTPD (31% identical), SFTPA1 (24% identical), SFTPA2 (24% identical).
Diseases named in the same sentence as COLEC10 in open-access papers:
COLEC10 is named in the same sentence as 23 diseases in open-access papers, as found by Europe PMC text mining. Sharing a sentence is not in itself a finding about the gene and the disease. The quoted sentences say what the papers report.
3MC syndrome (8 papers, 2017 to 2025). "Up to now, only three 3MC syndrome patients with mutations in the COLEC10 gene have been reported, and here, we report the fourth patient and the first homozygous frameshift mutation." (PMID 34636477, 2021). "Up to now, only three 3MC syndrome patients with mutations in the COLEC10 gene have been reported, and here, we report the fourth patient and the first homozygous frameshift variant." (PMID 34636477, 2021). "Through functional studies and gene expression evaluation in the mouse embryo, they demonstrated that mutations in the COLEC10 gene and CL‐L1 deficiencies as a result are consistent with 3MC syndrome." (PMID 34636477, 2021). "To date, 16 mutations in MASP-1/3, 12 mutations in COLEC11 and three in COLEC10 associated with 3MC syndrome have been identified." (PMID 32751929, 2020). "In this study, we could find a frameshift deletion variant in the COLEC10 gene in the patient showing 3MC syndrome phenotypes." (PMID 34636477, 2021). "In summary, we have described here a new gene, COLEC10, that when mutated causes 3MC syndrome." (PMID 28301481, 2017). "To validate COLEC10 mutations as causative of 3MC syndrome we determine its expression pattern in the developing mouse embryo and we further demonstrate the in vitro functional consequences of COLEC10 mutations, and present evidence that CL-L1 act as a cellular chemoattractant." (PMID 28301481, 2017). "Collectin-10 (COLEC10), COLEC11, and MASP1/3 polymorphisms have been identified in Mingarelli, Malpeuch, Michels, and Carnevale (3MC) syndrome." (PMID 41155225, 2025). "In 2017, Munye and colleagues, identified three compound heterozygous mutations [p.(Arg9Ter), p.(Gly77GlufsTer66), p.(Cys176Trp)] in COLEC10, as a novel gene in three Pakistani patients with 3MC syndrome." (PMID 34636477, 2021). "As mentioned, so far 11 mutations in the COLEC11 gene, three in the COLEC10 gene, and 16 in the MASP1/3 gene associated with 3MC syndrome have been described." (PMID 32751929, 2020). "3MC syndrome is a rare genetic disorder inherited through an autosomal recessive inheritance pattern caused by mutations in one of three genes: COLEC11, COLEC10, and MASP1." (PMID 34589314, 2021). "This is supported by relationships between MASP1/3, COLEC10, and COLEC11 gene mutations and the incidence of 3MC syndrome, associated with craniofacial abnormalities such as radioulnar synostosis high-arched eyebrows, cleft lip/palate, hearing loss, and ptosis." (PMID 32751929, 2020). "This may be supported by the relationship between MASP1/3, COLEC10, and COLEC11 mutations and the incidence of 3MC syndrome, associated with craniofacial abnormalities." (PMID 32751929, 2020). "Several different potentially deleterious mutations in genes of the lectin arm of the complement system - such as MASP1, COLEC10, and COLEC11 genes – have been described in patients with 3MC syndrome." (PMID 32116493, 2020). "Further studies, however, are necessary to further understand the mechanisms by which dysfunctional MASP1, COLEC10, and COLEC11 genes may lead to 3MC syndrome." (PMID 32116493, 2020). "Further studies, however, are necessary to better understand the mechanisms by which dysfunction of MASP1/3, COLEC10, and COLEC11 genes may lead to the 3MC syndrome." (PMID 32751929, 2020).
liver cancer (5 papers, 2019 to 2025). An epithelial or non-epithelial malignant neoplasm that arises from the liver. "Consistent with the findings by Zhang and Wu, this study, which included two validation cohorts, showed that low COLEC10 expression in liver cancer tissues correlates with a poor prognosis and is intimately linked to HCC disease progression." (PMID 40026364, 2025). "Apart from the development disorder, overexpression of COLEC10 in hepatocellular carcinoma cells induces endoplasmic reticulum stress and inhibits the progression of liver cancer." (PMID 38036508, 2023). "We found COLEC10, GPAA1, CD5L, NCSTN, SNX27, GOLPH3L, and HIST2H2AC genes were associated with worst OS (HR < 1) in female liver cancer patients." (PMID 31216110, 2019). "Interestingly, the mining of the RNA-seq data from The Cancer Genome Atlas (TCGA) indicates the high expression of COLEC10 in the liver cancer tissue predicts a better prognosis of the patients." (PMID 38036508, 2023). "In the present study, leveraging GEO liver cancer-related expression data, we identified 42 genes that are commonly downregulated in HCC tissues compared to normal tissues, with COLEC10, KMO, and GNMT being the most frequently altered." (PMID 40026364, 2025). "COLEC10 suppresses HCC stemness by downregulating the Wnt/β-catenin pathway, which represents a promising target for liver cancer stem cell therapy." (PMID 40636781, 2025).
hepatocellular carcinoma (4 papers, 2023 to 2025). A malignant tumor that arises from hepatocytes. "miR‐452‐5p facilitated hepatocellular carcinoma cell proliferation, migration, and invasion by targeting COLEC10." (PMID 37014625, 2023). "Immunohistochemical analysis of clinical hepatoma tissue samples revealed that COLEC10, KMO, and GNMT proteins were predominantly localized to the cytoplasm of hepatoma cells in all samples." (PMID 40026364, 2025).
acute liver failure (2 papers, 2021 to 2023). Rapid deterioration of liver function causing encephalopathy and coagulopathy. "The serum concentration of COLEC10 in patients with acute liver failure and cirrhosis is higher than healthy people." (PMID 38036508, 2023).
Cirrhosis (2 papers, 2023 to 2025). A chronic disorder of the liver in which liver tissue becomes scarred and is partially replaced by regenerative nodules and fibrotic tissue resulting in loss of liver function. "Next, 12 cases of biopsy samples collected from patients diagnosed as hepatitis and cirrhosis were stained for COLEC10 and COL1A1." (PMID 38036508, 2023). "Concurrently, multivariate analysis established multinodular tumor, cirrhosis, BCLC staging, CLIP staging, and COLEC10 expression as independent prognostic factors for OS in HCC patients." (PMID 40026364, 2025). "The IHC showed that the expression of COLEC10 was decreased and the expression of COL1A1 was increased in cirrhosis compared to hepatitis." (PMID 38036508, 2023).
liver fibrosis (2 papers, 2020 to 2023). "Collectively, our results identify the producing cell type and the biological functions of COLEC10, highlight the role of COLEC10 in the pathogenesis of liver fibrosis and the promising clinical value as a diagnostic and prognostic markers of CLD." (PMID 38036508, 2023). "The mRNA expression of genes associated with the pathogenesis of liver fibrosis is measured in the COLEC10 overexpression group and vector control group." (PMID 38036508, 2023). "The results demonstrated the expression of COLEC10 was significantly negatively correlated with progression of liver fibrosis." (PMID 38036508, 2023). "COLEC10 is also mainly expressed in the hepatic stellate cells of human livers and the expression of COLEC10 is decreased with the progression of liver fibrosis." (PMID 38036508, 2023). "In conclusion, the COLEC10 overexpression in vivo promoted the mRNA expression of Col1a1 and Vegfa, which suggested that the COLEC10 is associated with the ECM alteration and angiogenesis in the pathogenesis of liver fibrosis." (PMID 38036508, 2023). "The liver-specific serum type of AAV was chosen to overexpress COLEC10 in CCl4-induced liver fibrosis mice models." (PMID 38036508, 2023). "Altogether, we conclude that the C-type lectin COLEC10 is predominantly produced by the hepatic stellate cells and involved in the pathogenesis of liver fibrosis." (PMID 38036508, 2023). "The results implied the mRNA expression of Colec11 and Colec10 were downregulated in the hepatic stellate cells in the early phase of liver fibrosis." (PMID 38036508, 2023). "The results demonstrate the COLEC10 promoted the expression of Col1a1 and Vegfa, which indicates the function of COLEC10 is associated with the ECM alteration and angiogenesis during the liver fibrosis." (PMID 38036508, 2023). "We hypothesized that the expression of COLEC10 was negatively correlated with severity of liver fibrosis." (PMID 38036508, 2023). "The results revealed the COLEC10 is involved in the pathogenesis of liver fibrosis." (PMID 38036508, 2023). "The expression of COLEC10 is decreased during the progression of liver fibrosis." (PMID 38036508, 2023). "Accordingly, we speculated that the downregulation of Colec10 facilitated activation of hepatic stellate cells and accelerated liver fibrosis." (PMID 38036508, 2023). "Since the Colec10 and Colec11 were highly expressed in the qHSCs, we assumed the two C-type lectins could be involved in the pathology of liver fibrosis." (PMID 38036508, 2023).
liver diseases (1 paper, 2023). "In view of the current research about the function of COLEC10, little is known about its role in the liver diseases." (PMID 38036508, 2023). "The results suggest the function of COLEC10 is closely correlated with tissue repair mechanism in liver diseases." (PMID 38036508, 2023).
Michels syndrome (1 paper, 2017). "We found one patient diagnosed with Michels syndrome harbouring deletions in COLEC10 (NM_006438.4), another member of the collectin family." (PMID 28301481, 2017).
tumor (6 papers, 2020 to 2025). "COLEC10 expression significantly correlated with tumor location, TNM staging, serum alpha-fetoprotein (AFP) levels, and survival rates." (PMID 40026364, 2025). "PPI network analysis implicated CCBE1 and FCN3 as candidates for interaction with COLEC10, with their reduced expressions in tumor tissues and significant correlation with patient survival." (PMID 40026364, 2025). "In the future, it will be necessary to verify the effect of COLEC10 on tumor growth in vivo through animal experiments, such as the nude mouse subcutaneous transplantation tumor model." (PMID 40026364, 2025). "The genes repressed in both GE1-HCC and GE2-HCC included those with supposed tumour-inhibiting activity, e.g. CXCL14, CCBE1, IGFBP1, RND3, BMP10 and COLEC10, which encode proteins involved in extracellular matrix remodelling, migration and the immune response." (PMID 33541355, 2021). "Our findings suggest that COLEC10 may exert its tumor-suppressive effects, in part, through the modulation of the Hedgehog signaling pathway and the PI3K-AKT signaling cascade, both of which are critical in HCC progression." (PMID 40026364, 2025). "Analysis via the HCCDB database demonstrated alterations in the PPI network of COLEC10 between HCC tissues and their adjacent non-tumor tissues." (PMID 40026364, 2025). "The expression patterns of COLEC10, KMO, and GNMT in LIHC were correlated with tumor staging (P(NF) < 0.05)." (PMID 40026364, 2025). "Subsequent in vitro experiments demonstrated that COLEC10 overexpression exerted a suppressive effect on HCC cell growth, migration, and invasion, proposing a potential role for COLEC10 as a tumor suppressor in HCC." (PMID 40026364, 2025). "The expression levels of COLEC10, KMO, and GNMT were observed to be markedly reduced in tumor tissues compared to matched normal counterparts (P < 0.05)." (PMID 40026364, 2025). "In conclusion, our study aimed to identify hub genes involved in HCC by WGCNA of data from the TCGA database and concluded that three functional genes (TGFBR3, COLEC10, and FYN) are highly differentially expressed in tumor and nontumor tissues." (PMID 35397600, 2022).
cancer (3 papers, 2019 to 2025). A tumor composed of atypical neoplastic, often pleomorphic cells that invade other tissues. "Further investigation, particularly of COLEC10, demonstrated its robust association with cancer progression, underscoring its importance as a target for HCC research and potential treatment." (PMID 40026364, 2025). "EMT is a critical process in cancer metastasis, and its regulation by COLEC10 in HCC cells was investigated." (PMID 40026364, 2025).
COLEC10 also shares sentences with these, for which no sentence is quoted: lung carcinoma (3 papers); alcoholic cirrhosis (1); COVID-19 (1); diabetes (1); diabetic foot (1); fetal growth restriction (1); genetic disorder (1); Hepatitis (1); Intellectual disability (1); lung adenocarcinoma (1); lupus glomerulonephritis (1); myeloma (1); respiratory distress syndrome (1).